CD24 (CD24 molecule)
Diseases named in the same sentence as CD24 in open-access papers (continued):
Sharing a sentence is not in itself a finding about the gene and the disease.
tumor (continued). "Additionally, uBCOs exhibited the expression of designated tumor stem-cell markers, in detail, CD24 and CD44, further highlighting their potential for studying BC stem cells and their capacity to expansion, as well as their responses to systemic anti-cancer agents in BC." (PMID 37681920, 2023). "Furthermore, the anti-CD24 mAb, G7 mAb, enhances the inhibitory effect of cetuximab on tumor proliferation in vivo, suggesting that CD24 might promotes the growth of tumor cells through the regulation of EGFR expression." (PMID 38313430, 2023). "Therefore, blocking CD24 or Siglec-10 with monoclonal antibodies enhances the ability of macrophages to phagocytose tumor cells and inhibit tumor growth; this approach may be useful for patients who are unresponsive to meditators of the PD-1/PD-L1 pathway." (PMID 35418152, 2022). "As CCA cells use EVs to interact with surrounding mesenchymal stem cells to modulate the microenvironment and enhance the tumor growth, it can be postulated that the reduction of these cell interactions via CD24 and CD44 loaded EVs after SIRT may reduce tumor growth and progression." (PMID 35954154, 2022). "Although CD24 is an accepted CSC biomarker, whether their expression (overexpression or lack of expression) is associated with stem-like properties and tumourigenic potential seems to be context-dependent, varying across tumour types." (PMID 35326385, 2022). "Thus, triggering the immune system by immune‐modulating therapy might also lead to CD24 downregulation, which in turn may render the tumor cells more sensitive toward cisplatin." (PMID 34293822, 2022). "Notably, the expression of CD24 in solid tumors has been correlated with worse prognosis, including the presence of more aggressive features and their metastatic spread in vivo; in fact, CD24 expression has been shown to promote tumor growth and malignant behavior in a dose-dependent manner." (PMID 36013184, 2022). "To investigate the mechanism underlying the superior abilities of tumour initiation, formation, invasion and metastasis of the ALDH+ CD44+ CXCR4+ CD24+ subpopulation, we performed microarray analysis to identify the DEGs between the ALDH+ CD44+ CXCR4+ CD24+- and ALDH− CD44− CXCR4− CD24−-PCa cells." (PMID 34247196, 2021). "Indeed, in the in vivo xenograft model, CD24−/low/CD44+ cell-injected mice exhibited greatly increased tumor growth and lung metastasis, accompanied by upregulated expression of EMT-related proteins and increased HIF-1α and ESM-1 levels in tumors and circulating LOX levels in plasma." (PMID 34502547, 2021). "Thus, CD24 expression could predict which patients may have tendencies to biochemical recurrence and possible recrudescence of the tumor." (PMID 33806857, 2021). "Nuclear localization of β-catenin in stable miR-146a expressing tumor was evident, however, less pronounced upon transient expression in cell lines, which likely indicates the equilibrium shift towards CSCs, due to prolonged expression of miR-146a with consequent reduction of CD24." (PMID 34712602, 2021). "Importantly, the mechanism leading to an increased surface CD24 expression in tumor cells under drug stress remains unknown." (PMID 34426608, 2021). "Besides, the addition of anti-CD24 antibody to the chemotherapy regimen may be beneficial to target chemotherapy-resistant tumor stem cells." (PMID 32765491, 2020). "In addition to CD47, tumor cells also highly express CD24 molecules to achieve immune escape." (PMID 33224886, 2020). "Notably, most tumor biomarkers, including CD24, are heterogeneously expressed." (PMID 33260974, 2020).
tumor (continued). "Also, in animal models of breast cancer and renal cell cancer, it has been demonstrated that platelets tend to adhere with increased affinity to angiogenic vessels, mediated by the upregulation of CD24 on tumor cells, thus releasing their pro-angiogenic content in the tumor microenvironment." (PMID 32257952, 2020). "Therefore, inhibiting these CD24-related upstream molecules of regulatory signaling pathways can effectively prevent tumor invasion and immune escape, improve the tumor microenvironment, and may have a positive effect on tumor treatment." (PMID 32765491, 2020). "Consequently, CD24’s tumor specificity should be exploited beyond fluorescent contrast agents." (PMID 33260974, 2020). "Thus, here we isolate by FACS the enriched population of BCSCs (ESA+-CD44+-CD24-/Low cells, from now on CD24-) and the so-called tumor-differentiated cells (ESA+-CD44+-CD24+ cells, from now on CD24+) from MCF7-Tet-On-SrcDN, and test their capacity of self-renewal." (PMID 32673341, 2020). "Since we previously observed a strong effect of holo-LCN-2 on tumour cell migration, we then performed qRT-PCR analysis of migration-associated genes, such as the transcription factor Snail, the epithelial marker CDH1, the mesenchymal marker fibronectin as well as the stemness markers CD24 and CD44." (PMID 31772326, 2020). "However, the anti Her2/neu CAR-T cells only demonstrated significant efficacy when epidermal growth factor receptor (EGFR) was highly expressed in the majority of cells within the tumor, whereas anti-CD24 CAR-T was successful despite low levels of CD-24 expression within the tumor." (PMID 31878090, 2019). "Moreover, CD44 is a marker, together with CD24, of tumor-initiating cells or tumor stem cells." (PMID 31534630, 2019). "However, both how CD24 overexpression induces autophagy and whether autophagy activation contributes to tumor cell drug resistance or is a mechanism of resistance remain uncertain." (PMID 29844385, 2018). "Although our unpublished data indeed show a negative regulation by IRISOE on CD24 transcription through increasing Twist expression, this could not explain the fact that many primary IRISOE/TNBC tumors and tumor cell lines maintain cytoplasmic CD24 expression (see discussion)." (PMID 28052035, 2017). "The slightly positive expression of CD24 in the primary tumor and metastases might be mainly due to the complicated microenvironment of tumor, which included blood vessels and other microenvironmental cells that were CD24+." (PMID 29062075, 2017). "Thus, combining anti-IGF-I receptor and anti-ATF5 therapies may show good efficiency in attenuating aggressive CD24-positive tumor growth." (PMID 28785242, 2017). "Given that GD2, similar to previously reported CD44 and CD24 cell surface markers in other cancers, is able to separate cancer cells into two populations with differing tumor-initiating potential we hypothesize that GD2 would express CD44hiCD24lo cancer cell fraction." (PMID 29221154, 2017). "Subsequently, CSCs were identified in solid tumours by Al-Hajj and co-workers who reported in 2003 that only a subpopulation of breast cancer cells staining, positively for CD44 and negatively for CD24, could re­ initiate tumours with the cellular heterogeneity typical of the original tumour." (PMID 29211293, 2017). "Accumulated evidences demonstrated that CD24 belonged to the glycosylphosphatidylinositol-anchored membrane protein, and the targeting CD24 therapeutic strategies have been positively verified in many human carcinomas by inhibiting tumor proliferation and metastasis." (PMID 27494878, 2016). "However, CD24 function depends on the tumor entity and subcellular localization." (PMID 27203385, 2016). "To investigate whether CD24 plays a functional role in tumorigenesis in these models, we crossed CD24 deficient mice with MMTV-PyMT, Apc1572T/+ and TRAMP mice, and assessed the influence of CD24 deficiency on tumor onset and tumor burden." (PMID 26978528, 2016).
tumor (continued). "In this context, HES6 may enhance tumour initiation by supporting expression of CD24." (PMID 25864518, 2015). "Since one of the important markers of MM stemness, CD24, progressively increased in the individual generations of tumour-derived spheres, in particular in those derived from Ist-Mes-2 cells), we tested whether it is important for MM stemness and for their efficacy to form tumours." (PMID 25932953, 2015). "Moreover, CD24+ cells gave rise in vivo to the CD24− that comprised the bulk of the tumor." (PMID 26040280, 2015). "When compared to tumor of origin IL-6 expression was significantly elevated (10-106 fold) in the CD49f−CD24−(MM) population and a majority of CD49f+CD24−(PM) populations, while significantly decreased an average 100 fold in the CD49f+CD24+(PP) populations when compared to tumor." (PMID 25269750, 2014). "Since xenograft tumors generated from both CD24+/CD44+ and CD24-/CD44+ cells showed the similar immunohistochemical staining, we hypothesized that the CD24+/CD44+ cells may have been generated during the in vivo tumor growth from CD24-/CD44+ cell subpopulation." (PMID 24612587, 2014). "Furthermore, studies performed on NPC tumor biopsies or cell lines with enhanced invasiveness or epithelial-mesenchymal transitions also revealed enhanced expression of Sox2, Oct-4, and Nanog, similar to the findings reported here on CD24+ cells." (PMID 24955581, 2014). "However, CD90+ cells were found clustered around CD24+ malignant ducts, which further suggests that CD90 may be involved in the tumor-stroma interactions and play a role in cancer-associated fibroblasts to promote pancreatic tumorigenesis and development." (PMID 25536077, 2014). "Tumor cells with increased CD24 expression acquired the capacity to form stabilized platelet-tumor thrombi and then adhered to endothelial cells at the distal metastatic sites, which protected tumor cells from destruction and promoted tissue penetration and tumor extravasation." (PMID 25503963, 2014). "Interestingly, the effects of recombinant CCN2 peptide on U-CH1 cells were more pronounced under normoxia than hypoxia, promoting increased expression of CCN1, CCN2, CCN3 and CCN5, the notochord-associated markers SOX5, SOX6, T, CD24, and FOXA1 as well as increased tumour-sphere formation." (PMID 25541962, 2014). "Also known as heat stable antigen, CD24 is a glycosylphosphatidylinositol (GPI)-anchored membrane protein that has been implicated in tumorigenesis, progression, metastasis and poor prognosis for a variety of tumor types." (PMID 23533633, 2013). "Studies have suggested that CD24 expression may enhance the metastatic potential of tumor cells." (PMID 24179538, 2013). "This indicates that CD24 could be a significant marker in tumor prognosis and diagnosis." (PMID 23401782, 2013). "Kaplan-Meier analysis showed that the presence of CD44+/CD24-/low tumor cells was significantly associated with shorter DFS compared with the absence of CD44+/CD24-/low tumor cells (22.9 ± 2.2 months versus 35.9 ± 3.8 months; Pearson chi-square, 10.696, p = 0.001)." (PMID 22762532, 2012). "This indicates that CD24 could be a significant marker in tumour prognosis and diagnosis." (PMID 22693526, 2012). "Furthermore, clinical studies indicate that CD44+/CD24- tumor-initiating cells express an invasive gene signature and may be associated with distant metastases." (PMID 21824412, 2011). "Moreover, long term culture of the tumor biopsies revealed HBCEC populations expressing certain precursor cell-like and tumor-associated markers, including CD24, CD44 and CD227, respectively, which was paralleled by little if any senescence and a detectable telomerase activity." (PMID 19751512, 2009). "Furthermore, Weinberg and colleagues recently reported that mammosphere-forming and tumor-initiating capacities reside within CD24+ freshly isolated normal mammary cells, but when these cells are briefly cultured the CD24- population was enriched with cancer stem cells." (PMID 18241344, 2008).
tumor (continued). "Moreover, CD24-mediated binding to P-selectin on endothelial cells and platelets may facilitate the exit of tumor cells from the bloodstream and potentiate metastasis." (PMID 18433506, 2008). "Furthermore, the tumours that arise in mice injected with purified CD44+CD24− LNCaP cells are phenotypically diverse, containing primarily CD44−CD24− and CD44−CD24+ cells and only a small percentage of CD44+CD24− cells, similar to tumours derived from injecting the total LNCaP cell line." (PMID 18268494, 2008). "CD24 is a ligand of P-selectin, an adhesion receptor on activated endothelial cells and platelets, and could thus contribute to the metastasising capacities of CD24-expressing tumour cells." (PMID 12610508, 2003). "Mechanistically, SLC38A4 downregulates the expression of "don't eat me" molecule CD24, which mediates the roles of SLC38A4 in Kupffer cells phagocytosis and tumor liver metastasis." (PMID 42067616, 2026). "In mice carrying the CD24 overexpression MTCQ1-GFP grafts, the spleen also enlarged despite the tumor burdens being equivalent to those of the controls." (PMID 41585138, 2026). "Siglec‐GΔITIM relieved CD24‐induced immunosuppression, significantly enhanced TAM phagocytic activity in HCC models, and inhibited tumor progression." (PMID 41426206, 2026). "This study shows the diverse immune cell infiltration related to CD24 expression across MOCL-1 and MTCQ1 tumors, most likely due to the variation in CD24 expression level or tumor microenvironment in grafts." (PMID 41585138, 2026). "Additionally, CD24 deletion in mouse models of BC xenotransplantation has been shown to inhibit primary tumor growth and, more importantly, may hinder the colonization and growth of cancer cells in distant organs such as the lungs by reducing the formation of microvessels and lymphatics." (PMID 40223929, 2025). "CD24 expression decreased by 57% in the SEA 0.3 group (P = 0.07) and by 61.5% in the SEA 3 group (P = 0.07) compared to control tumor samples." (PMID 40371330, 2025). "CKS1B knockdown significantly reduced the self-renewal capacity and number of CSCs, as evidenced by in vitro tumor sphere formation, increased CD44+CD24+/CD133+ cell populations, and decreased expression of CSCs markers (ABCG2, C-MYC, ALDH1, BMI-1)." (PMID 39897042, 2025). "CD90, CD133 and CD44s expression was detected in less than 5% of tumor buds, while CD166, CD24 and ALDH1 were expressed in 34%, 16.2% and 16.5% of cases, respectively, in a study evaluating eight CSC biomarkers." (PMID 40564019, 2025). "The accumulation of CD4-CD8+TCRβ+CD24+ cells in the thymus suggests the onset of T-ALL and migration of thymic tumor cells to the periphery such as spleen." (PMID 40534857, 2025). "The CD24 and SIGLEC-10 axis is largely unchanged, however there is increased expression of CD47 on tumour cells and high levels of SIRPα on macrophages." (PMID 39788719, 2025). "Tumor cells exploit similar evasion strategies by overexpressing these inhibitory signals (e.g., CD47, CD24) or reprogramming macrophages toward pro-tumoral phenotypes via tumor microenvironment (TME) remodeling." (PMID 40380196, 2025). "We obtained 44 paired tumor samples (pre- and post-chemotherapy) from the Tumor Biobank, assessing BCSC biomarkers (CD44, CD24, and ALDH1), PD-L1, and percentages of stromal tumor-infiltrating lymphocytes (TILs)." (PMID 40362201, 2025). "Specifically, CD24-positive NPC cells exhibited a higher proliferation rate, better ability to form tumorspheres, and increased chemotherapy resistance and tumor initiation in immunocompromised mice." (PMID 40647395, 2025). "These cells, which are marked by molecules such as CD24, CD44, CD133, and Hes3, have the ability to self-renew and differentiate into more mature cancer cells, aiding in tumor progression and the formation of pseudopalisading necrosis." (PMID 40223032, 2025).
tumor (continued). "Collectively, these findings identify CD24 as a pivotal regulator within the CRC senescence network, coordinating tumor progression through concurrent enhancement of proliferative capacity, metastatic potential, and apoptosis resistance." (PMID 40777020, 2025). "To further analyze the lipid metabolism pathway in GC cells, we identified tumor cells using the GC-specific markers EPCAM and CD24." (PMID 40694956, 2025). "Tumor cells can evade TAM clearance by overexpressing antiphagocytic surface proteins known as “don't eat me” signals, such as, CD47 and CD24." (PMID 41354057, 2025). "A phase I clinical trial of the anti-CD24 monoclonal antibody NXA01 has also been approved, and it is noteworthy for its ability to selectively target and kill CD24-positive tumor cells; the outcomes of this trial are eagerly anticipated." (PMID 40486886, 2025). "Recent research has highlighted the roles of CD24 and the transferrin receptor 1 (TFR1) in facilitating tumor immune escape, as well as the importance of iron homeostasis in cancer development, particularly in HCC." (PMID 41551164, 2025). "PAR2 also plays a role in cancer development, promoting tumour proliferation, angiogenesis and expression of immune checkpoint inhibitors (like PD-L1, CD47 and CD24)." (PMID 40806209, 2025). "We found that CSCs expressed high levels of tumor stemness genes (PROM1, CD24, CD47, ANPEP, ALDH1A1, OLFM4, and SOX9), and demonstrated a high cancer stemness score, along with activation of the cancer driver genes EGFR and ERBB2." (PMID 39950944, 2025). "Transcriptomic profiling revealed that PDGCOs_1 expressed elevated levels of tumor epithelial and stem cell markers, such as EPCAM, CDH1, ALDH3A1, CA9, CD24, and CD133." (PMID 40723172, 2025). "This downregulation correlates with increased expression of CD24 and TFR1, suggesting a potential mechanism by which miR-10a-5p influences tumor immune escape and iron metabolism." (PMID 41551164, 2025). "This reduces on‐target and off‐tumor toxicity (OTOT), resulting in a wider safety window for CD24‐targeted therapies." (PMID 41354057, 2025). "For instance, CD24-/CD44+ breast CSCs are mesenchymal-like, primarily quiescent, and localized at the tumor-invasive front, whereas ALDH+ breast CSCs are epithelial-like and proliferative, and more centrally located." (PMID 39919692, 2025). "CD24, CLDN3, WFDC2, and TACSTD2 genes were present in all the tumour clusters of all samples, and the genes C1orf194, C20orf85, MS4A8, ODF3B, RSPH1, and TPPP3 appear to be co‐expressed." (PMID 41160707, 2025). "From the 29 selected TNBC patients, tumor samples from 22 were available for biomarker analysis including BCSC markers (CD44, CD24, ALDH1) and immunogenic markers (PD-L1, and TILs)." (PMID 40362201, 2025). "The reduction in CD44v6 was accompanied by decreased levels of CD44, CD24, and CD133, which are widely recognized as key CSC markers involved in regulating self-renewal, differentiation potential, and tumor aggressiveness (p < 0.001)." (PMID 40069421, 2025). "The overexpression of antiphagocytic signals (“don't eat me”) has been correlated with tumor progression, such as signaling involving CD47 and CD24." (PMID 41354057, 2025). "Next, we performed scRNA-seq and identified five distinct tumor cell clusters within C5-HGSC: immune-responsive, EMT-like, neuronal-like, CD24+ stem cell-like, and invasive." (PMID 41444249, 2025). "However, it should not be overlooked that due to the expression of CD24 on the surface of normal cells and potential off-target effects, it may cause a certain degree of damage to non-tumor cells in the body." (PMID 40486886, 2025). "Only 6 of these miRNAs were shared as differentially enriched biomarkers between the HER2+ and CD24+ EVs, suggesting that these EV subpopulations represent complementary biomarkers for the classification of BI-RADS 4 breast lesions." (PMID 40405296, 2025).